LCN2 (lipocalin 2)
Description:
Iron-trafficking protein involved in multiple processes such as apoptosis, innate immunity and renal development. Binds iron through association with 2,3-dihydroxybenzoic acid (2,3-DHBA), a siderophore that shares structural similarities with bacterial enterobactin, and delivers or removes iron from the cell, depending on the context. Iron-bound form (holo-24p3) is internalized following binding to the SLC22A17 (24p3R) receptor, leading to release of iron and subsequent increase of intracellular iron concentration. In contrast, association of the iron-free form (apo-24p3) with the SLC22A17 (24p3R) receptor is followed by association with an intracellular siderophore, iron chelation and iron transfer to the extracellular medium, thereby reducing intracellular iron concentration. Involved in apoptosis due to interleukin-3 (IL3) deprivation: iron-loaded form increases intracellular iron concentration without promoting apoptosis, while iron-free form decreases intracellular iron levels, inducing expression of the proapoptotic protein BCL2L11/BIM, resulting in apoptosis (By similarity). Involved in innate immunity; limits bacterial proliferation by sequestering iron bound to microbial siderophores, such as enterobactin. Can also bind siderophores from M.tuberculosis.
Synonyms: NGAL; 24p3; MSFI; p25
Tractability: Small molecule: a structure with a bound ligand is known; it has a high-quality binding pocket. Antibody: UniProt places it where antibodies can reach, with high confidence; its Gene Ontology location is reachable by antibodies, with high confidence; UniProt predicts a signal peptide or a membrane-spanning region. PROTAC: its protein half-life has been measured.
Gene: Protein-coding gene on chromosome 9 (128,149,071 to 128,153,453, forward strand). Ensembl gene ENSG00000148346.
Subcellular location: Secreted; Cytoplasmic granule lumen; Cytoplasmic vesicle lumen
Subcellular location (Human Protein Atlas): Endoplasmic reticulum; Predicted to be secreted
Pathways (Reactome):
Immune System: Interleukin-4 and Interleukin-13 signaling; Metal sequestration by antimicrobial proteins; Neutrophil degranulation
Transport of small molecules: Iron uptake and transport
Gene Ontology:
Molecular function: enterobactin binding; identical protein binding; iron ion binding; iron ion sequestering activity; protein binding; protease binding; small molecule binding
Biological process: defense response to bacterium; innate immune response; positive regulation of cold-induced thermogenesis; siderophore transport; acute-phase response; cellular response to amyloid-beta; cellular response to hydrogen peroxide; cellular response to hypoxia; cellular response to increased oxygen levels; cellular response to interleukin-1; cellular response to interleukin-6; cellular response to lipopolysaccharide; cellular response to nerve growth factor stimulus; cellular response to nutrient levels; cellular response to tumor necrosis factor; cellular response to X-ray; long-term memory; negative regulation of hippocampal neuron apoptotic process; positive regulation of apoptotic process; positive regulation of cell projection organization; positive regulation of endothelial cell migration; positive regulation of endothelial tube morphogenesis; positive regulation of gene expression; positive regulation of hippocampal neuron apoptotic process; positive regulation of iron ion import across plasma membrane; and 16 more
Cellular component: cytoplasmic vesicle lumen; endoplasmic reticulum; extracellular exosome; extracellular region; specific granule lumen
Genetic constraint (gnomAD): Loss-of-function variants: 27 observed, 27.41 expected, observed/expected ratio (o/e) 0.98, 90% interval 0.73 to 1.36. The upper end of that interval is the gene's LOEUF score, 1.36, which puts it in group 5 of 6, group 1 being the genes least tolerant of losing a copy. Missense variants: 224 observed, 249.13 expected, observed/expected ratio (o/e) 0.9, 90% interval 0.81 to 1. Synonymous variants: 94 observed, 105.28 expected, observed/expected ratio (o/e) 0.89, 90% interval 0.75 to 1.06.
Homologues: Orthologues: chimpanzee LCN2 (98% identical), chimpanzee LCN2 (96% identical), macaque LCN2 (90% identical), pig LCN2 (71% identical), rabbit LCN2 (68% identical), dog LCN2 (67% identical), rat Lcn2 (64% identical), mouse Lcn2 (62% identical). Paralogues in human: LCN12 (33% identical), PTGDS (29% identical), LCN15 (23% identical), LCN6 (18% identical), LCN10 (17% identical), LCN9 (17% identical), OBP2A (16% identical), OBP2B (16% identical), PAEP (14% identical), LCN1 (14% identical), LCN8 (12% identical), LCNL1 (11% identical).
Diseases named in the same sentence as LCN2 in open-access papers:
LCN2 is named in the same sentence as 726 diseases in open-access papers, as found by Europe PMC text mining. Sharing a sentence is not in itself a finding about the gene and the disease. The quoted sentences say what the papers report.
acute kidney injury (606 papers, 2007 to 2026). Sudden and sustained deterioration of the kidney function characterized by decreased glomerular filtration rate, increased serum creatinine or oliguria. "LCN2 has previously been associated with acute kidney injury and is an established biomarker for kidney damage." (PMID 39000587, 2024). "Neutrophil gelatinase-associated lipocalin (NGAL) also called LCN2 (Lipocalin-2) has been shown to be a biomarker for acute kidney injury." (PMID 27446820, 2015). "LCN2 has been proven to differentially expressed between septic shock and sepsis in surgical patients, and has been reported as a potential biomarker of septic-shock-associated acute kidney injury." (PMID 36911395, 2023). "LCN2 is a well-established prognostic and diagnostic marker in acute kidney injury." (PMID 37298232, 2023). "This could point to urinary lipocalin-2 levels differentiating between the causes of acute kidney injury in liver cirrhosis." (PMID 37189804, 2023). "However, from the present findings KIM-1 and lipocalin-2 appear to be the most promising diagnostic markers of acute kidney injury." (PMID 25970334, 2015). "LCN2, also known as neutrophil gelatinase-associated lipocalin, has been extensively studied as a reliable biomarker for acute kidney injury (AKI) for a long time." (PMID 39613734, 2024). "The LCN2 gene, also known as lipocalin 2 or neutrophil gelatinase-associated lipocalin (NGAL), has emerged as a significant biomarker for a range of conditions, including acute kidney injury, Alzheimer’s disease, MS and depression." (PMID 40035034, 2025). "Lipocalin 2/neutrophil gelatinase‐associated lipocalin (Lcn2/NGAL) and KIM‐1 are markers of acute kidney injury." (PMID 40018982, 2025). "This deficiency has also been shown in mice transitioning from acute kidney injury (AKI) to CKD, while upregulation of Havcr1 and Lcn2 act as early biomarkers for AKI." (PMID 40374849, 2025). "Lipocalin-2 (Lcn2) is a sensitive early marker for acute kidney injury, delayed graft function and acute rejection of kidney transplants." (PMID 41488635, 2025). "LCN2 is secreted in high amounts into the urine and blood from tubular cells during acute kidney injury (AKI) before serum creatinine rises." (PMID 38379702, 2024). "Lipocalin-2 is considered an ideal biological early marker for acute kidney injury and can predict clinical outcomes." (PMID 38178854, 2024). "Clinically, LCN2 belongs to the lipocalin family of proteins and is already considered an important marker for prognosis and diagnosis in acute kidney injury and various malignancies." (PMID 37298232, 2023). "Critically ill patients with acute kidney injury also displayed high urinary lipocalin-2 levels, and this was related to disease progression and mortality." (PMID 37189804, 2023). "We also demonstrated an independent correlation of serum and urine lipocalin-2 levels with acute kidney injury in HFRS." (PMID 38004329, 2023). "LCN2 in the peripheral circulation can be used as a biomarker for numerous diseases, such as metabolic syndrome, acute kidney injury, cardiovascular disease or various brain diseases." (PMID 37543589, 2023). "One of the most indicative biomarkers for acute kidney injury (AKI) is Neutrophil Gelatinase Associated Lipocalin (NGAL), also called lipocalin-2, produced from the nephron in response to tubular epithelial damage." (PMID 36344956, 2022). "LCN-2 has been recognized as a promising inflammatory marker involved in many acute inflammatory damages in many diseases such as acute kidney injury, ischemic stroke, myocardial ischemia-reperfusion injury, etc.." (PMID 36419491, 2022). "LCN2 is widely reported to be involved in acute kidney injury and chronic kidney disease and is a biomarker of hepatic ischemia reperfusion injury severity stages." (PMID 35990970, 2022).
acute kidney injury (continued). "Although there are several renal failure markers for renal failure, including urine protein, lipocalin 2, and cystatin C, creatinine is granted as the primary one as an excellent clearance level in urine, interpretative simplicity, and high susceptibility." (PMID 35207080, 2022). "Lipocalin-2/NGAL is an iron-carrying protein that is expressed by tubular epithelial cells following acute kidney injury and chronic kidney disease." (PMID 35355862, 2022). "LCN2 has been identified as a potential biomarker for several common inflammatory diseases including acute kidney injury, lupus nephritis, cardiovascular diseases, or intestinal inflammation." (PMID 32605546, 2020). "Lcn-2 fluctuated in parallel with plasma urea during the study, and both markers increased sharply on the last week, indicating the development of renal failure." (PMID 32481551, 2020). "Acute kidney injury triggers the release of lipocalin-2 (Lcn-2), which is involved in both renal injury and recovery." (PMID 33065981, 2020). "NGAL, also named lipocalin-2, is a secretory protein that is released during renal injury and serves as a marker of acute kidney injury." (PMID 31218128, 2019). "For example, before the major pathological changes, the increasing mRNA expressions of Kim-1, Lcn2, Clu, and Vim revealed injury in various models of acute kidney injury." (PMID 27983637, 2016). "More recently a systematic review and meta-analysis on LCN2 in acute kidney injury (AKI) or failure investigating more than 50 studies concluded that blood LCN2 could be used as a diagnostic marker for AKI in newborns." (PMID 27729871, 2016). "Although HAVCR1 (KIM-1) and LCN2 (NGAL) have been characterized as sensitive markers of acute kidney injury, recent reports revealed that their kidney expression levels also increased in progressive renal disease." (PMID 26317775, 2015). "The mRNA expression of well-known acute kidney injury (AKI) biomarkers like LCN2 and HAVCR1/KIM-1 has been found to be significantly increased in recipients developing delayed graft function (DGF)." (PMID 26249165, 2015). "Lipocalin-2 (Lcn-2), also named Neutrophil-gelatinase associated lipocalin (NGAL) and 24p3, is a new marker in acute kidney injury as well as chronic kidney disease." (PMID 23861783, 2013). "Lipocalin-2 (Lcn-2) is involved in divergent processes such as acute kidney injury or bacterial host defence." (PMID 23861783, 2013). "In addition, MAPK, Fas, and lipocalin-2 can provide new therapeutic targets for acute kidney failure." (PMID 38178854, 2024). "Moreover, LCN2 is increased in atherosclerosis and upregulated by hypoxia and MI, being actually considered a potential biomarker of early ischemic acute kidney injury." (PMID 32143690, 2020). "Previous studies indicated that Lcn-2 might serve as a good predictor of acute kidney failure in critically ill patients, indicating the need for renal replacement therapy." (PMID 33065981, 2020). "Lcn-2 is a prominent candidate marker for improving the timely diagnosis of acute kidney injury." (PMID 23861783, 2013). "Lcn2 is known as an acute-phase protein that can protect the body against acute ischemic renal injury, therefore it is suggested that administration of exogenous Lcn2 may exerts remarkable protection in AKI (Acute Kidney Injury )." (PMID 23493520, 2012). "It has been demonstrated that Lcn2 accumulates in the blood and urine of patients with acute kidney injury (AKI) and the blood of patients with bacterial infections." (PMID 40569986, 2025). "The levels of Lcn2 in blood serum and urine serve as potential biomarkers for acute kidney injury (AKI) and renal graft rejection." (PMID 41488635, 2025). "Lcn2 delivers Fe to epithelia through endocytosis and endosomal acidification in a process similar to cellular Tf handling in order to stimulate their growth and differentiation, and promote repair and regeneration of damaged epithelia, e.g., during acute kidney injury (AKI)." (PMID 34298880, 2021).
acute kidney injury (continued). "Therefore, the understanding of molecular and genetic mechanisms that control Lcn-2 signaling and recycling of iron could offer new perspectives for future therapeutic avenues in acute kidney injury and progressive interstitial fibrosis." (PMID 32188161, 2020). "Polymicrobial sepsis can initiate acute kidney injury (AKI), characterized by the release of kidney damage markers, such as creatinine and lipocalin-2 (Lcn-2), into the serum." (PMID 33348637, 2020). "Thus, an increase of LCN2 in plasma could be due to the presence of a hypoxic tumor or to acute kidney injury." (PMID 25467539, 2014). "However, with urinary lipocalin-2 levels being elevated in patients with sepsis, urinary infections or cardiopulmonary bypass surgeries, the prognostic utility of urinary lipocalin-2 concentrations for acute kidney injury appears limited, which is especially relevant for patients in intensive care." (PMID 37189804, 2023). "Furthermore, Lcn-2 is considered a real-time, sensitive biomarker for renal diseases and not only plays a role as a biomarker for disease states, but in certain cases, also actively protects against acute kidney injury (AKI), such as ischemia–reperfusion injury." (PMID 37958332, 2023). "The presence of LCN2 in urine indicates acute kidney injury (AKI)." (PMID 34257811, 2021). "Moreover, in cases of acute kidney injury (AKI), Lcn2 is strongly expressed in epithelia of damaged nephrons and is released into body fluids." (PMID 26595644, 2016). "A study indicated a correlation between septic shock and acute kidney injury (AKI), revealing that the genes PTX3, VMP1, OLFM4, SLPI, TIMP1, LCN2, and S100A9 are strongly correlated with novel biomarkers implicated in the onset and progression of sepsis‐associated acute kidney injury (SSAKI)." (PMID 41394771, 2025). "Sepsis may also induce acute kidney injury (AKI), and studies showed that VMP1, SLPI, PTX3, TIMP1, OLFM4, LCN2, and S100A9 genes were markedly correlated with the development and progression of septic-shock-associated AKI." (PMID 36299685, 2022). "In chronic renal failure, Viau and coworkers recently provided compelling evidence that Lcn-2 plays a key role in the progression of renal failure via EGFR-mediated proliferation using a non-inflammatory polycystic kidney disease models." (PMID 23861783, 2013). "Despite the reported relationship of LCN2 with cardio-metabolic disease and acute kidney injury, to date it is not clear whether circulating levels of LCN2 change during normal aging across the adult lifespan." (PMID 39830147, 2025).
Sepsis (309 papers, 2008 to 2026). Sepsis is defined as life-threatening organ dysfunction caused by a dysregulated host response to infection. "In summary, our study provides a novel pathogenic link between sepsis and encephalopathy, in which sepsis upregulates LCN2, triggering mitochondrial dysfunction and neuronal loss, thus leading to synaptic and cognitive impairments." (PMID 40025014, 2025). "Next, we explored the effects and underlying mechanisms of LCN2 on sepsis-related neuronal death using primary hippocampal neurons treated with ACM." (PMID 40025014, 2025). "In the current study, we elucidated an abnormal upregulation of LCN2 protein in the LPS-induced mouse model of sepsis, which correlates with neuronal loss in the hippocampus." (PMID 40025014, 2025). "Here, we demonstrated that mice with sepsis exhibit neuronal loss, which mediates sepsis-related synaptic and cognitive deficits accompanied by LCN2 upregulation." (PMID 40025014, 2025). "In contrast, upregulated LCN2 mediated the bacteriostatic effect of E. coli in WT mice, protecting mice from death caused by sepsis." (PMID 38093296, 2023). "Several of the top regulated genes that are shared between CLP-induced and LPS-induced septic hearts, such as Cxcl13, Lcn2, and Serpina3m, have been implicated in the development of endothelial hyperpermeability and human sepsis." (PMID 37510271, 2023). "Lcn2-deficient mice have increased intracellular labile iron, delayed hypoferremia, and are more susceptible to mortality from endotoxin-induced sepsis from E. coli-derived LPS." (PMID 36054235, 2022). "The level of LCN-2 in plasma was markedly higher in patients with severe sepsis and was associated with higher cardiac biomarkers and lower LVEF." (PMID 36419491, 2022). "Nevertheless, LCN2 has been shown to have both protective and pathogenic roles in organ damage with rodents or humans, including hepatic injury, sepsis, obesity, and diabetes." (PMID 34844610, 2021). "Protective function of LCN2 is documented in experiments with Lcn2-deficient mice, which are highly prone to bacterial infection and sepsis." (PMID 34594242, 2021). "After validation, plasma hsa-mir-92a was confirmed as a diagnostic biomarker for sepsis-induced coagulopathy and related to global coagulation index and plasma lipocalin-2 level." (PMID 32075600, 2020). "Notably, EV-based panels (miR-122-5p, miR-125b-5p, miR-223-3p, OLFM4, and LCN2) have been found to be associated with the severity or prognosis of sepsis, with promising AUC values." (PMID 39901167, 2025). "Our findings revealed that neuronal loss in sepsis mice results from LCN2 upregulation." (PMID 40025014, 2025). "An increased LCN2 at early sepsis may act as a potential biomarker for sepsis-associated encephalopathy." (PMID 40025014, 2025). "Additionally, downregulation of LCN2 in sepsis mice attenuated neuronal loss, synaptic damage, and cognitive impairments probably by restoring mitochondrial function." (PMID 40025014, 2025). "Thus, our findings suggest a previously undiscovered etiopathogenic relationship between sepsis and cognitive impairments that is linked to an increased LCN2 and the potential of LCN2-based therapeutics for encephalopathy such as SAE." (PMID 40025014, 2025). "Low expression of ARHGEF10L in CD14 + monocytes is associated with increased death from sepsis, and the list included genes related to anti-bacterial activity (LCN2), regulation of TLR4 responses (SLC15A3), LPS sensitivity and autophagy (RUBCNL and SLC8A1) and apoptosis (FAS, TNFRSF21, TNFRSF8)." (PMID 39730996, 2024). "In addition, MPO and LCN2 have been identified as critical genes in sepsis and sepsis-related ARDS, with LCN2 showing diagnostic value in sepsis-related ARDS." (PMID 37822934, 2023). "In addition, it has been described to capture bacterial siderophores produced by pathogenic bacteria, such as E. coli and, indeed, Lcn2-deficient mice are prone to infection and sepsis." (PMID 37092455, 2023).